UBE3A (ubiquitin protein ligase E3A)
Diseases named in the same sentence as UBE3A in open-access papers (continued):
Sharing a sentence is not in itself a finding about the gene and the disease.
Angelman syndrome (continued). "The development of Angelman syndrome is not solely due to the mutation or deletion of UBE3A as many other genes are present spanning this chromosomal region." (PMID 38248358, 2023). "Angelman syndrome (AS) is a rare neurodevelopmental disorder characterized by the absence of a functional UBE3A gene, which causes developmental, behavioral, and medical challenges." (PMID 37495977, 2023). "Angelman Syndrome (AS) is a rare genetic disorder caused by lack of maternal UBE3A protein due to a deletion of the chromosome 15q11.2-q13 region, uniparental paternal disomy, imprinting center defect, or pathogenic variant in the UBE3A gene." (PMID 37762921, 2023). "Low and high levels of UBE3A or a lack of UBE3A function are linked to disorders such as Angelman syndrome (AS)." (PMID 38248358, 2023). "Another example of a dosage-sensitive gene is UBE3A, whose mutation can cause either Angelman syndrome or non-syndromic autism as a result of loss-of-function or overexpression, respectively." (PMID 34807307, 2022). "Consequently, we observe significant circadian phenotypes in all three mouse models of Angelman syndrome, and our results concur with an earlier circadian study of the roles of Ube3a in tissue cultures." (PMID 35401134, 2022). "Of note, among the top transcripts upregulated by SNI in the mPFC of SNI female mice, Snhg14 encodes a long non-coding RNA that regulates the expression of ubiquitin protein ligase E3A (Ube3a), which is known to critically implicate in the social interaction dysfunction in Angelman’s syndrome." (PMID 35663269, 2022). "Here, we tested the hypothesis that multidimensional analysis of mouse behavioral data could accurately distinguish the genotype of Ube3a mutants (a model of Angelman syndrome (AS)) from wild-type littermates." (PMID 36192373, 2022). "Angelman Syndrome (AS) is a severe neurodevelopmental disorder, caused by the neuronal absence of the ubiquitin protein ligase E3A (UBE3A)." (PMID 36613751, 2022). "It is likely that the paternal isodisomy in this patient resulted in simultaneous loss of heterozygosity in the imprinting UBE3A gene and the paternally derived pathogenic DUOX2 E520D missense substitution, resulting in a complex clinical phenotype, i.e., Angelman syndrome with hypothyroidism." (PMID 36028527, 2022). "The reason to extend our search terms was that, historically, UBE3A was first discovered in non-Angelman-related (cancer) research and only some years after its discovery it was associated with Angelman syndrome." (PMID 35637341, 2022). "Deviations in delta power from a human natural history model in Angelman syndrome can detect antisense oligonucleotide-mediated improvement in Ube3a expression in Angelman syndrome mice and may be relevant for human clinical trials." (PMID 35611307, 2022). "To facilitate these experiments, we crossed Ube3a+2 mice to Angelman syndrome (AS) model mice (AS/Ube3a+2), as the latter are devoid of UBE3A expression in mature neurons, effectively providing a blank backdrop against which Ube3aOE transgene expression can be plainly observed." (PMID 36134658, 2022). "Genetic analysis included Angelman syndrome testing (15q11-q13 methylation pattern and UBE3A sequencing), karyotype, fragile X syndrome testing, subtelomeric MLPA (SALSA MLPA P070, MRC Holland), and 60K array Comparative Genomic Hybridization (aCGH) (Agilent Technologies) with normal results." (PMID 34121983, 2021). "This UBE3A deficiency can be potentially treated by gene replacement therapy and, indeed, intrahippocampal AAV9-UBE3A injection caused some improvements in a mouse model of Angelman syndrome." (PMID 34690692, 2021). "While the role of these lncRNAs in AD pathology is unknown, SNHG14/UBE3A-ATS has been proposed as a therapeutic target for Angelman syndrome due to its role in silencing the expression of UBE3A." (PMID 35052379, 2021).
Angelman syndrome (continued). "These abnormalities point to a function of UBE3A in experience-dependent plasticity during development that could play a role in the cognitive deficits observed in Angelman syndrome." (PMID 32982715, 2020). "Interestingly, only very recently, the critical importance of the nuclear isoform of UBE3A for the Angelman syndrome phenotype was characterized." (PMID 31988313, 2020). "Our findings provide important considerations for upcoming clinical trials in which UBE3A gene expression is reactivated and suggest that even transient UBE3A reinstatement during a critical window of early development is likely to prevent most adverse Angelman syndrome phenotypes." (PMID 31143434, 2019). "Although we do not know how the first 3 weeks of postnatal brain development in mice translates to human brain development, our results suggest that even transient UBE3A reinstatement during a critical window of early development is likely to prevent most adverse Angelman syndrome phenotypes." (PMID 31143434, 2019). "As reviewed by Matsui and Corey (2017), in Angelman syndrome model mouse, the administration of antisense oligonucleotides (ASOs), which target the Ube3a‐ATS lncRNA for degradation, partially reversed some cognitive defects associated with the disease in the animals." (PMID 31572441, 2019). "Here we propose that modulating protein ubiquitination may represent a therapeutic approach for Angelman syndrome patients that lack UBE3A activity in the brain." (PMID 31130875, 2019). "We are interested in elucidating the molecular mechanisms underlying Angelman syndrome, a rare neurological disease caused by the lack of functional E3 ubiquitin ligase UBE3A in the brain." (PMID 31130875, 2019). "It is hypothesized that increased methylation of UBE3A-ATS may increase expression of the paternally inherited UBE3A gene and ameliorate the phenotypes in Angelman syndrome." (PMID 31640736, 2019). "Therefore, identifying the DUB responsible for deubiquitinating UBE3A substrates is of pivotal relevance in the development of successful therapies to treat Angelman syndrome." (PMID 31130875, 2019). "The role of UBE3A in EEG phenotype should also be examined in Prader-Willi syndrome, another 15q disorder caused by deletions/uniparental disomy of the paternal/maternal allele, the opposite of Angelman syndrome." (PMID 31312421, 2019). "These anatomical data may help to elucidate the role of UBE3A in Angelman syndrome and autism spectrum disorder." (PMID 30364390, 2018). "Small nucleolar RNA host gene 14 (SNHG14) is located within the Prader-Willi critical region and extends in antisense into the region of the ubiquitin protein ligase E3A (UBE3A) gene, whose deficiency in brain cells in children causes neurogenetic disorders, such as Angelman syndrome." (PMID 29552296, 2018). "An opposite scenario was observed in Ube3A hemizygous mice modeling Angelman syndrome (another disorder characterized by autism and ID), in which Homer 1a levels are reduced in the hippocampus, resulting into an enhanced coupling of mGlu5 receptors with long Homer isoforms." (PMID 29615849, 2018). "Angelman syndrome (AS) is a rare neurodevelopmental disorder caused by lack of expression of the maternal ubiquitin-protein ligase E3A (UBE3A) gene in the brain." (PMID 29037196, 2017). "E3 ubiquitin ligase E6-AP is encoded by UBE3A gene; mutations and genetic imprinting in this gene result in Angelman syndrome (AS), which can be described by symptoms like frequent laughter, tremor, ataxia, abnormal gait, seizures, and neurological impairments." (PMID 28579943, 2017).
Angelman syndrome (continued). "This new Angelman syndrome iPSC line allows to study imprinted gene regulation on both parental alleles and to dissect molecular pathways affected by the absence of UBE3A protein." (PMID 27484051, 2016). "Therefore, after methylation study and UBE3A gene analysis, the first line of investigation for Angelman-like Syndrome should be array CGH." (PMID 26942024, 2016). "Furthermore, loss of UBE3A has been associated with enhanced delta oscillations and suppression of ventral striatal GABA co-release in mouse models of Angelman syndrome, underscoring the relationship between the ubiquitin ligase and GABAergic transmission." (PMID 27977700, 2016). "Interestingly, most of these mutations are catalytically defective, thereby indicating the importance of UBE3A enzymatic activity role in the Angelman syndrome pathology." (PMID 25633294, 2015). "A proportion of the Angelman syndrome patients bear UBE3A point mutations, which do not interfere with the expression of the full-length protein, however, these individuals still develop physiological conditions of the disease." (PMID 25633294, 2015). "In the context of Angelman syndrome, such ATFs could be used to reactivate the paternal UBE3A that is silenced by imprinting, or inactivate the paternal UBE3A-ATS antisense transcript." (PMID 24946931, 2014). "These advances may result in an eventual therapy for Angelman syndrome, allowing for the expression of paternal UBE3A and perhaps a full phenotypic rescue." (PMID 24946931, 2014). "Similarly, daily injections fully rescued TBS-induced actin polymerization, LTP, and context fear memory in the Ube3a mouse model of Angelman syndrome, again in tests carried out 24 h after the last injection of the short half-life compound." (PMID 23966908, 2013). "Disruption of the maternal allele, through genomic deletion, paternal uniparental disomy, imprinting defects, or point mutations, leads to the absence of UBE3A expression in neuronal tissues and hence Angelman syndrome." (PMID 24385930, 2013). "Therefore, our research confirmed the clinical benefit of activating paternal Ube3a in treating Angelman syndrome and provided a mouse model as the positive control for future drug testing." (PMID 24385930, 2013). "More than 50 mutations in the UBE3A gene (E6-AP ubiquitin protein ligase gene) have been found in Angelman syndrome patients with no deletion, no uniparental disomy, and no imprinting defect." (PMID 23256887, 2012). "The analysis identified Angelman syndrome gene product UBE3A as an ASPM interactor." (PMID 21633703, 2011). "Although hyperactivity and social-seeking behavior are characteristic phenotypes of Angelman Syndrome in humans, the Ube3a deficient mouse model does not reproduce these phenotypes in comparison to their wild-type littermates." (PMID 21235769, 2011). "GABRB3 and UBE3A are well-characterized candidate genes for ASD because they are associated with normal brain development and have been shown to be reduced in idiopathic autism, Angelman syndrome and Rett syndrome." (PMID 22152151, 2011). "Examined OD plasticity in a maternal Ube3a knockout mouse model of Angelman syndrome." (PMID 21826280, 2011). "Linkage disequilibrium at the Angelman syndrome gene UBE3A in autism families." (PMID 21034472, 2010). "Therefore, cystoscopy screening in patients with Angelman syndrome may be considered a topic for further study, given the potential role of the UBE3A gene in malignancy regulation." (PMID 41200642, 2025). "However, many neurodevelopmental disorders, such as Angelman syndrome, have a critical window that may limit the effectiveness of therapeutics like UBE3A reinstatement in adults, where neuronal circuits are already established and compromised." (PMID 40076922, 2025).
Angelman syndrome (continued). "In addition, UBE3A silencing by UBE3A-ATS activation might adversely induce the pathology of Angelman syndrome." (PMID 41152294, 2025). "Moreover, PCS prevents hippocampal downregulation of Angelman Syndrome gene, Ube3a." (PMID 41081549, 2025). "Notably, enzymatically competent UBE3A is essential to prevent Angelman syndrome pathogenesis." (PMID 36134658, 2022). "However, the coactivator function of UBE3A in the Angelman syndrome was little explored." (PMID 33995501, 2021). "Loss-of-function mutations in the maternal UBE3A copy or de novo deletions of chromosomal region 15q11-q13, in which UBE3A resides, cause the severe neurodevelopmental disorder Angelman syndrome (AS), characterized by abnormal motor development, lack of speech, seizures, and a happy demeanor." (PMID 34366796, 2021). "However, in Ube3a deleted mice that are raised in darkness, spine density and dynamics were indistinguishable with controls, which indicates that decreased spine density in Angelman syndrome model mice reflects impaired experience-driven spine maintenance." (PMID 32982715, 2020). "Importantly, the exact level of UBE3A in the brain is crucial: its lack leads to Angelman syndrome (AS; OMIN#105830), while its increase can cause non-syndromic autism spectrum disorder (ASD) and Dup15q syndrome (OMIN#608636)." (PMID 31798818, 2019). "Similarly, based on our results, we propose that attenuating the activity of USP9X may contribute to enhance the ubiquitination levels of UBE3A substrates that might be decreased in Angelman syndrome patients." (PMID 31130875, 2019). "UBE3A gene is imprinted in the brain with preferential maternal-specific expression particularly in the neuron and loss of activity of the maternally inherited UBE3A causes Angelman syndrome (AS), characterized by severe mental retardation, lack of speech, seizures and autistic features." (PMID 30568575, 2018). "Interestingly, impaired conditioned fear and decreased marble-burying were reported in mice with deletion of maternal E3 ubiquitin ligase Ube3a, a model for Angelman syndrome, again highlighting the critical role of protein ubiquitination in cerebellar homeostasis." (PMID 30222779, 2018). "Angelman syndrome (AS) (OMIM # 105830) is caused by the absence or non-functioning of the maternal ubiquitin-protein ligase E3A gene (UBE3A, OMIM #601623) on chromosome 15q11.2-q13 and occurs in 1 in 12,000–20,000 individuals, affecting males and females equally." (PMID 28895939, 2017). "HAP1 accumulation increases autophagy influx in Angelman syndrome mice, and HAP1 is one of the UBE3A substrates." (PMID 40076922, 2025). "For instance, the Snord115 gene cluster can influence the silencing state of the UBE3A gene in neurons by regulating the expression of UBE3A-ATS, offering a novel therapeutic target for Angelman syndrome." (PMID 41244840, 2025). "There are three neurological disorders, Rett syndrome, Angelman syndrome, and autism, which show lower GABRB3 and UBE3A gene expression, along with the manifestation of clinical phenotypes like intellectual disability and epilepsy." (PMID 38248358, 2023). "In the case of patient E7, a 43-year-old man and the eldest in the cohort, the presence of a deletion affecting the entire UBE3A and GABRB3 genes led to the suspicion of Angelman syndrome." (PMID 38328757, 2023). "Low levels of UBE3A decreased the ubiquitination of PTPA, which further accelerated PP2A holoenzyme assembly, and enhanced its activity in angelman syndrome." (PMID 37461021, 2023).
Angelman syndrome (continued). "Moreover, one could with similar ease envision that multimerization of active and inactive UBE3A molecules produces a significant dominant-negative effect, diminishing overall UBE3A enzymatic function and tending toward a scenario reminiscent of Angelman syndrome." (PMID 36134658, 2022). "Next, we complimented our original search for “Angelman syndrome” with two additional searches for “UBE3A” and “E6AP”." (PMID 35637341, 2022). "An example is the gene coding of the ubiquitin protein ligase E3A (UBE3A), which is also disrupted in Angelman syndrome, which shares some clinical symptoms with ASD." (PMID 34204536, 2021). "The Foundation for Angelman Syndrome Therapeutics (FAST) funded the generation of a genetic rat model of AS via a 90-kb deletion on chromosome 1, which includes the entire Ube3a gene." (PMID 32066685, 2020). "Although Ube3a is the causative gene in Angelman syndrome and may be contributing to 15q duplication autism, many of the features observed in the Ube3a deficient AS mouse model are not the opposite of what is observed in the Ube3a duplication autism mouse models." (PMID 22916201, 2012). "It was found that Angelman syndrome patients (lacking neuronal UBE3A) have increased plasma APP and Aβ peptides compared to controls." (PMID 40076922, 2025). "On the other hand, Angelman syndrome (OMIM #105830) is a rare NDD characterized by the lack of expression of the maternal ubiquitin–protein ligase E3A (UBE3A) gene in the brain." (PMID 38616334, 2024). "Moreover, the use of AntagoNATto suppressed the gene UBE3A-AS, which is known to suppress the paternal copy of the ubiquitin protein ligase E3A gene (UBE3A), which improves cognitive deficits of the Angelman Syndrome in mice model." (PMID 38841098, 2024). "Ube3a is homologous to the E6AP C-terminus (HECT) E3 ligase and is a critical factor for normal neurodevelopment, as its loss of function in the brain leads to Angelman syndrome." (PMID 35742859, 2022). "In a mouse model for Angelman Syndrome, adult reinstatement of Ube3a does not rescue behavioral phenotypes found in the Ube3a mouse." (PMID 36304100, 2022). "For example, restoration of Ube3a expression in young mice leads to reversal of many adverse phenotypes in a model of Angelman syndrome, but not all autism-related phenotypes are reversed when the gene is activated in older animals." (PMID 34807307, 2022). "Angelman syndrome (AS) is a genetic neurodevelopmental disorder due to the absence of the E3-ligase protein, UBE3A." (PMID 33420192, 2021). "In the model of Angelman syndrome, genetic strategies have been developed to investigate timed reinstatement of gene expression in mice lacking the UBE3A gene on neurodevelopmental outcomes." (PMID 34654371, 2021). "Lack of UBE3A expression results in Angelman syndrome, while UBE3A overexpression, due to genomic 15q duplication, results in autism." (PMID 32532103, 2020). "For the last few decades, since the discovery of UBE3A as an E3 ligase and the finding of its involvement in Angelman syndrome, the biological effects of altered UBE3A have not been completely elucidated." (PMID 32455880, 2020). "The general notion of impaired experience-dependent plasticity in Angelman syndrome is reinforced by the observation that MD, which usually induces an OD shift in the visual cortex of wild type mice, does not have such an effect in Ube3a-deleted animals." (PMID 32982715, 2020). "The lack of functional UBE3A E3 ubiquitin ligase in the brain is responsible for a rare neurodevelopmental disorder called Angelman syndrome (AS)." (PMID 31130875, 2019).